STAT3 (signal transducer and activator of transcription 3)
Diseases named in the same sentence as STAT3 in open-access papers (continued):
Sharing a sentence is not in itself a finding about the gene and the disease.
tumor (continued). "This goes hand-in-hand with increased levels of cleaved caspase-3 and high SOCS1 in these tumours, which leads to suppression of STAT3 signalling." (PMID 25820993, 2015). "This review summarizes recent findings on the role of STAT3 in tumor initiation, progression and angiogenesis, focusing on genitourinary tumors." (PMID 28031890, 2015). "The study finds that STAT3 activation plays an important role in the tumor cell survival, proliferation, angiogenesis, invasion, metastasis, and immune escape." (PMID 26788112, 2015). "STAT3 upregulation has pro-tumorigenic functions that enhance tumor cell growth, invasion and metastasis in a variety of cancers." (PMID 26389681, 2015). "Surprisingly, our results show that STAT3 functions as tumour suppressor in KrasG12D/+ lung tumours as well as KRAS mutant human AC cell lines." (PMID 25734337, 2015). "To determine the impact of STAT3 inhibition on tumor growth in vivo, we subcutaneously injected AsPC-1(STAT3-shRNA) and AsPC-1(Vector) cells into nude mice on either side of the abdomen." (PMID 25961376, 2015). "Short hairpin-mediated IL-8/STAT3 double knockdown resulted in a reduction in tumour growth, tumour vascularization and macrophage infiltration compared with STAT3 single knockdown within the human A549 xenograft model." (PMID 25734337, 2015). "We further assessed the anti-tumor effects of JAK2/STAT3 inhibitor and MEK inhibitor as single agents and in various combinations in K-Ras mutated pancreatic and colon cells in vitro, as well as nude mice tumor model in vivo." (PMID 25961376, 2015). "Taken together, our data support a role for STAT3 in activating tumor invasion and enhancing the EMT-like phenotype in cisplatin-selected resistant ATRT cells." (PMID 25638155, 2015). "Although TGF-β and STAT3 are known to enhance tumor angiogenesis, TβRI inhibition with SB505124 did not suppress endothelial activation in vitro." (PMID 25762644, 2015). "We examined the effects of EB on tumor cells that had different levels of STAT3 phosphorylation and found that the inhibition of EB on tumor cell growth was correlated with the level of the STAT3 phosphorylation in the cells." (PMID 26010889, 2015). "Cucurbitacins B, D, E, I, F, O, P, and Q are known to suppress proliferation of tumor cells through inhibition of STAT3 phosphorylation." (PMID 26169986, 2015). "Intraperitoneal injection of BSN and paclitaxel into athymic nu/nu female mice bearing subcutaneous A549 xenografts resulted in significant suppression of tumor progression and inhibition of STAT3 activation in tumor tissues." (PMID 25788267, 2015). "Our study for the first time shows the role and mechanism of miR-23a in tumor radioresistance, which highlights the radiosensitizing potential of miR-23a/IL-8/Stat3 signaling axis in NPC and perhaps in other cancers." (PMID 26314966, 2015). "STAT3 is a known oncogene and survival factor that promotes cancer cell proliferation, tumor angiogenesis, and inflammation." (PMID 25762644, 2015). "Various cellular factors have recently emerged as important elements in maintaining the survival and proliferation of CRC tumor cells, including signal transducer and activator of transcription 3 (STAT3)." (PMID 25789077, 2015). "Stat3, an oncogenic transcriptional factor that is activated to initiate transcription of Stat3-targeted genes, is important in cell proliferation, invasion, and tumor formation." (PMID 25607111, 2015). "In the current study, ectopic expression of Snail rescued the shSTAT3-suppressed expression of Nanog and Sox2, self-renewal ability, and tumor-initiating abilities in ATRT-CisR/sh-STAT3 cells." (PMID 25638155, 2015). "In particular, after TARGIT treatment, they observed that various proteins including IL-6, MCP-1 and IL-8, and STAT3-drived pathways involved in controlling tumour cell growth and motility, were deregulated." (PMID 25705130, 2015).
tumor (continued). "As shown in 8B, significantly increased binding of STAT3 to the ANGPTL4 promoter was observed in Ad-GSCs as compared to bulk tumor cells." (PMID 25955030, 2015). "We demonstrate that STAT3 knockdown can reduce self-renewal, migration, and tumor formation of a TIC population in BM." (PMID 26314961, 2015). "Metformin suppressed tumor growth in xenografts by preferentially inhibiting nuclear translocation of NF-κB and phosphorylation of STAT3 in cancer stem cells." (PMID 25811972, 2015). "Through their functional interaction, NF-κB and STAT3 collaboratively promote tumor development via induction of pro-tumorigenic genes including genes in angiogenesis and hypoxia, chemokines and immunosuppressive cytokines." (PMID 26501341, 2015). "The tumor tissues of IL-21 KO-Apcmin/+ mice exhibited reduced activation of STAT3/NF-kB and this was evident in both epithelial and immune cells." (PMID 25839161, 2015). "Inhibiting activated STAT3 signaling contributes to angiogenesis inhibition, tumor growth arrest, and metastasis suppression." (PMID 25789853, 2015). "Having demonstrated the importance of STAT3-mediated repression of CXCL1 in tumour cells in vitro and in vivo, we set out to mechanistically interrogate this pathway further." (PMID 25734337, 2015). "IL-11 as well as IL-6 activates STAT3, which is closely related to growth, differentiation and metastasis of cancer cells in the tumour microenvironment." (PMID 28781374, 2015). "Tumor-associated macrophages release angiogenic cytokines that modulate RCC angiogenesis by activating NF-κB and STAT3 signaling." (PMID 28031890, 2015). "In clinical HCC specimens, GADD45G expression is inversely correlated with phosphorylated Stat3 expression in tumour cells and disease progression 91; this result was consistent with the relationship of Shp2 with Stat3 36,37." (PMID 26088100, 2015). "The purpose of this study was to characterize expression and activation of STAT3 in feline OSCC cell lines and tumor samples and to investigate the biologic activity of a novel, allosteric STAT3 inhibitor, LLL12, in feline OSCC cell lines." (PMID 26272737, 2015). "Accumulating evidences indicate that inhibition of STAT3 enhances radiation sensitivity in various tumor cells." (PMID 25605256, 2015). "Increased expression of p-STAT3 is significantly related with tumor cell differentiation (Odds ratio (OR) =1.895, 95% CI: 1.364-2.632, P<0.001) and lymph node metastases (OR=2.108, 95% CI: 1.104-4.024, P=0.024)." (PMID 26024373, 2015). "Overexpression of constitutively activated Stat3 in immortalized breast cells induced tumor formation." (PMID 25881542, 2015). "We observed that Stattic treatment reduced while exogenous expression of Stat3 enhanced in vitro tumor cell migration and invasion, as well as EMT-like molecular alterations in NPC cells." (PMID 25915430, 2015). "In all, 20–30% of tumour cells showed active STAT3 (tyrosine 705 phosphorylated STAT3) throughout tumour development." (PMID 25734337, 2015). "In liver, gastric or breast cells, IL-22 enhances tumor growth and progression by activating STAT3, followed by ERK1/2 and/or Akt phosphorylation." (PMID 25793261, 2015). "Aberrant activation of STAT3 has been found in many cancer cells, which contributes to carcinogenesis and tumor progression by promoting cell survival and growth." (PMID 26010889, 2015). "It is known that STAT3 is abnormally activated in many cancers and plays an important role in tumor proliferation and metastasis." (PMID 26245871, 2015). "There is, nevertheless, a prevailing perception that STAT3 signaling in the tumor environment is detrimental to anti-tumor immune function and represents a promising target to refocus tumor-promoting inflammation." (PMID 26393659, 2015). "Constitutively activated STAT3 promotes tumor cell cycle progression and survival, elicits angiogenesis, and suppresses the immune response to tumors." (PMID 26283544, 2015).
tumor (continued). "In our study, we found that cisplatin-selected resistant ATRT (CisR; ATRT-CisR) cells displayed higher STAT3 expression and it plays a role in oncogenic phenotype, such as cell motility, tumor invasion, and chemoresistance." (PMID 25638155, 2015). "Acetylated STAT3 induces promoter gene methylation of a major tumor-suppressor gene, ARHI, and thereby leads to the low expression level of ARHI and promotes cancer cell proliferation in ovarian cancer." (PMID 26631279, 2015). "Both activated STAT3, pSTA3, and acetyltransferase p300, a positive regulator of NF-κB/STAT3 signaling, were physically associated with NF-κB in IL6MYC tumor cells (lanes 7 and 8)." (PMID 25838973, 2015). "Our study suggests that coordination between STAT3 and miR-21 regulate the metastatic behavior of BMICs by promoting migration and self-renewal of tumor stem cell populations, tumor cell proliferation, survival and migration." (PMID 26314961, 2015). "Immunohistochemical analysis showed that MIF expression was ~2-fold higher, LC3 expression increased significantly by ~4-fold and STAT3 phosphorylation was 1.5-fold higher in ConA-treated tumor lesions compared with the control groups." (PMID 26633714, 2015). "Whereas STAT1 is usually considered to be a tumour suppressor, the role of STAT3 is thought to be oncogenic." (PMID 25880691, 2015). "Treatment of either cetuximab-sensitive or cetuximab-resistant cells with cetuximab and STAT-3 decoy resulted in significant reductions in tumor volume compared to cetuximab with a control mutant decoy." (PMID 26458879, 2015). "STAT3 activation can stimulate oncogenic transformation in cultured cells and tumor formation in nude mice." (PMID 25961376, 2015). "We next examined the safety and efficacy of inhibiting Src and Stat3 in vivo in two xenograft tumor models." (PMID 26625308, 2015). "While it is intriguing that PCSCs utilize PI3K/AKT, RAS/MAPK and STAT3 signaling to self-renew and maintain their presence within the tumor, these same pathways are also required for PCa cell proliferation and survival, tumor angiogenesis and metastasis." (PMID 25595909, 2015). "As a result, the cells show activation of key signal transduction pathways, including PI3K-AKT-mTOR, BRAF-MEK-MAPK, and STAT3 that have roles in promoting tumor growth, survival, and metastasis." (PMID 25897429, 2015). "Overall, our data establishes a novel interaction between Cav-1 and both JAK/STAT3 and JNK signaling in tumor cells, and we postulate that Cav-1 and caveolae directly promotes activation of STAT3 and JNK pathway activation through Src." (PMID 26065715, 2015). "JAK1 and STAT3 mutants result in a hyperactivated STAT3, which sustains cell transformation, and whose pharmacological ablation produces tumor cell growth inhibition." (PMID 26501073, 2015). "Stat3 upregulates VEGF expression in tumor cells and that VEGF induces the activation of VEGFR2 in endothelial cells." (PMID 25881542, 2015). "Specifically, phosphorylated STAT3 has been shown to be upregulated in both tumor and normal epithelium from HNSCC patients as compared to epithelium from non-cancer patients." (PMID 26272737, 2015). "A recent paper by Lee and colleagues documents that CD24 is important for self-renewal of liver TICs and their propensity to form tumours via a complex regulation involving STAT3 and NANOG." (PMID 25932953, 2015). "In pre-clinical models, constitutive STAT3 activation alone results in malignant transformation and inhibition of STAT3 activity results in arrest of tumor development and apoptosis." (PMID 25914882, 2015). "We demonstrated that cisplation can activate “oncogenic-type” of drug resistance and Snail plays a crucial role in STAT3-dependent induction of oncogenic phenotype, such as cisplatin resistance, tumor invasion and cancer stem-like properties." (PMID 25638155, 2015).
tumor (continued). "Since active STAT3 in tumors influences tumor survival, angiogenesis, metastasis, chemoresistance and immune evasion, too, we finally looked for a regulation of STAT3 phosphorylation targeted by CB1 inhibition." (PMID 26008966, 2015). "In conclusion, we provide the first evidence that de-regulated Jak3/STAT3/STAT5 signalling in CTCL cells represses the expression of the gene encoding miR-22, a novel tumor suppressor miRNA." (PMID 26244872, 2015). "QPCR analysis confirmed that the level of Nanog and Sox2 were significantly decreased in xenograft tumor sections from ATRT-CisR/sh-STAT3-transplanted mice compared with the levels observed after all other treatments." (PMID 25638155, 2015). "After treatment with S3I-201, a chemical probe inhibitor of STAT3 activity, the tumor foci in the lungs significantly decreased." (PMID 25992623, 2015). "PTK6 expression was induced in the mammary glands of ERBB2 transgenic mice before tumor development and correlated with activation of signal transducer and activator of transcription 3 (STAT3) and increased proliferation." (PMID 26247733, 2015). "To further determine the potential role of STAT3 pathway in tumor initiation effect, we take advantage of spontaneous de novo HNSCC mice models for our tumorigenesis studies." (PMID 26556875, 2015). "Inhibition of STAT3 significantly decreased the pro-tumor activity of Bay60-6583 and reduced tumor VEGF expression." (PMID 26317647, 2015). "Both IL-6 and IL-8 have been found to promote an aggressive tumor microenvironment through activation of the STAT-3-NfKB signaling." (PMID 28203638, 2015). "Ptenpc−/− tumours showed strong Akt Ser473 phosphorylation and, unexpectedly, Stat3 Tyr705 and Ser727 phosphorylation suggesting maximal transcriptional activity of Stat3." (PMID 26198641, 2015). "Examples of cross-talk that are observed include the cross-talk between the Jak-STAT and NF-kappaB pathways or STAT3 signaling enabling cross-talk among tumor and immune cells, resulting in an immunosuppressive network." (PMID 25283527, 2015). "On the other hand, the potential for inhibition of STAT3 activation and immune modulation suggests possible adjuvant use of statins with tumor vaccines." (PMID 26343197, 2015). "In contrast to tumor and stellate cells, near complete inhibition of cytokine-induced STAT3 and STAT5 phosphorylation was observed after pre-treatment with BMS-911543." (PMID 26575024, 2015). "STAT3 is an important signal transducer and transcription factor in regulating genes critical for cell growth and is often activated in tumor cells." (PMID 26010889, 2015). "As mentioned, saw palmetto extract regulates the proliferation of tumor cells by inhibiting the STAT3 signaling pathway, but its effect on tumor metastasis and antiangiogenesis is not clear." (PMID 26788112, 2015). "All the mice were euthanized, the tumors were isolated and imaged and the tumor sample cells were harvested to extract protein for determination if HHT inhibited STAT3 phosphorylation via western blot." (PMID 26166037, 2015). "Researchers shown that suppressing STAT3 activation by triterpenoid compounds can inhibited macrophage polarization to M2 phenotype which are involved in tumor development and poor clinical prognosis." (PMID 26631279, 2015). "It was observed that many tumor cells, which display constitutive STAT3 activation in vivo, rapidly lose STAT3 phosphorylation once put into culture without neighboring immune or stromal cells." (PMID 26501341, 2015). "In this regard, recent studies have also investigated the potential role of STAT3 (coded at 17q21.2), showing a higher frequency of enhanced expression of STAT3 with increasing tumor grade." (PMID 25965831, 2015). "Although STAT5 responses can also contribute to anti-tumour immunity, the effects of STAT3 and STAT1 on tumour-associated inflammation are believed to be playing a leading role." (PMID 25880691, 2015).
tumor (continued). "STAT3 is found to be constitutively activated in cancer cells and the persistent activation of STAT3 in cancer cells mediates tumour-promoting inflammation." (PMID 26199948, 2015). "Screening of BMIC lines with a library of STAT3 inhibitors identified one inhibitor to significantly reduce tumor formation." (PMID 26314961, 2015). "Taken together, these findings indicate that down-regulation of miR-874 contributes to tumor angiogenesis through STAT3 in GC, highlighting the potential of miR-874 as a target for human GC therapy." (PMID 25596740, 2015). "Our results further encourage to regard STAT3 inhibitors as therapeutic option for cancer patients who develop cachexia, independently of their direct anti-tumor activity." (PMID 25460504, 2015). "Recent studies have shown that STAT3 activation in brain tumors, such as gliomas and medulloblastomas, is a prognostic indicator for malignant progression, tumor growth, and a low patient survival rate." (PMID 25638155, 2015). "Taken together, our results indicate that TRβ1 acts as a tumor suppressor via attenuation of PI3K-AKT/ERK/STAT3 signaling to reduce tumor growth by decreasing cell proliferation and increasing apoptosis, and by impeding tumor cell invasion." (PMID 25924236, 2015). "Stat3 signaling plays a role in promoting tumor via inducing the formation of tumor blood vessels, facilitating the accumulation of neutrophils, enhancing tumor cells’ ability to resist apoptosis, and constantly expanding the local inflammatory response." (PMID 25706309, 2015). "Stat3 controlled constitutive and inducible VEGFR2 expression in tumor-associated brain endothelial cells." (PMID 25881542, 2015). "STAT3 usually acts as a tumour promoter, although its role as a tumour-suppressor has been previously reported." (PMID 26500281, 2015). "Our findings imply that gp130 in hepatocytes is a main mediator for STAT3 activation in tumors having a significant impact on tumor progression." (PMID 25741592, 2015). "STAT3 activation leads tumor cells and Tregs to express molecules that are related to immune checkpoints, such as PD-L1, and eventually inhibit T cell function." (PMID 26167500, 2015). "We showed that blockade of p-STAT3 eliminated both bulk tumor and side population (SP) cells with characteristics of CSCs in vitro." (PMID 26556875, 2015). "Our studies have thus identified STAT3 and miR-21 as cooperative regulators of stemness, migration and tumor initiation in lung-derived BM." (PMID 26314961, 2015). "IL-23 produced by macrophages promotes tumor growth by activating STAT-3 in the macrophages and Treg cells." (PMID 26684834, 2015). "In contrast, ATRT-Par/Ctrl cells treated with cisplatin showed slow tumor growth in transplanted mice, and ectopic STAT3 effectively activated tumor growth of ATRT-Par/Ctrl cells in the transplanted mice." (PMID 25638155, 2015). "Ablating STAT3 through use of inhibitors or knock-out mice results in enhanced function of DCs, T cells, natural killer cells, and neutrophils in tumor-bearing mice and induces growth inhibition of established tumors." (PMID 25914882, 2015). "Since STAT3 was shown to mediate the effects of HO-1-derived and exogenous CO, we next looked at the effects of HO-1 in tumor microenvironment on STAT3 signaling." (PMID 26418896, 2015). "We have recently demonstrated that endothelial cell-secreted IL-6 regulates the rate of tumor growth via STAT3 signaling." (PMID 26287605, 2015). "A549 and H520 tumor cells were exposed to STAT3 siRNA (A549-siRNA-STAT3 or H520-siRNA-STAT3) or empty vector and then treated with rhIL-17 at 100 ng/ml for 24 h." (PMID 26524953, 2015). "It has been shown that tumour cell-specific Stat3 blockade leads to changes in the tumour microenvironment and increased immune cell infiltration." (PMID 25734337, 2015). "We further showed the immunohistochemical staining results of Ki67, CD34, p-VEGFR2 and p-STAT3, on tumor sections." (PMID 25789853, 2015).